KRAS (KRas proto-oncogene, GTPase)
Diseases named in the same sentence as KRAS in open-access papers (continued):
Sharing a sentence is not in itself a finding about the gene and the disease.
lung cancer (continued). "To further determine the effects of verteporfin in KRAS-mutant lung cancer cells, we interrogated cells treated with verteporfin at a range of doses by RNA-Seq." (PMID 33830081, 2021). "tested the system on lung cancer cell lines A549 and H23, both originating from NSCLC adenocarcinoma, in order to target the KRAS G12D mutation." (PMID 34781949, 2021). "They found that blockage of MEK and PI3K suppressed tumor growth in KRAS-driven lung cancer mouse models." (PMID 34347396, 2021). "We detected the expression of DACH1 in NSCLC cell lines, MRC5 cells and the KRAS-oncogene-driven lung cancer mice." (PMID 33435990, 2021). "In support of the contributory role of BLT2 in KRAS-driven lung cancer progression, IHC analysis of tissues obtained from patients with KrasG12D mutant malignant lung adenocarcinoma showed high levels of BLT2 expression." (PMID 34635780, 2021). "We analyzed single-cell sequencing data from the existing research and found that the epithelial cells at the resection margin of lung cancer were more likely to highly activate the genes related to lung cancer, such as KRAS, MET, and EGFR." (PMID 34094930, 2021). "It has been shown that KRAS regulates lipid homeostasis and Acyl-coenzyme A synthetase, an enzyme involved in fatty acid metabolism, essential for mutant KRAS lung cancer tumorigenesis in vivo." (PMID 33777798, 2021). "KRAS mutations are most typically identified in the tumors of smokers (particularly heavy smokers), with non or light smokers accounting for just 5–10% of KRAS-mutant lung cancers." (PMID 34692523, 2021). "This review describes the molecular characterization of KRAS mutant lung cancers from a biologic perspective to its clinical implications." (PMID 35096591, 2021). "Researches showed that AURKB is an important target for KRAS, therefore has the potential to serve as a target of KRAS-induced lung cancer." (PMID 33612479, 2021). "This suggests that the aetiology of mutations at the guanine in the first position of codon 12 in KRAS is likely different between lung cancer and other cancer types." (PMID 34521464, 2021). "Collectively, the findings demonstrated the anti-tumor effects of ISR inhibitors on mutant KRAS lung tumor growth in mice and their therapeutic potential for the treatment of lung cancer." (PMID 34330898, 2021). "used CRISPR in an in vivo setting of KRAS G12D mutant mice and investigated the function of three main chromatin regulatory genes in lung cancer initiation and progression." (PMID 34781949, 2021). "KRAS+ lung cancer is known to be dependent on HER2/HER3 signaling and often express ERβ, making it potentially responsive to a pan-HER inhibitor in combination with an ER blocker." (PMID 35008514, 2021). "As FGFR and PLK1 inhibitors are under active clinical development, our findings provide a new rationale of synergistic combination therapy that is readily translatable for patients with KRAS‐mutant lung cancer." (PMID 34369083, 2021). "For example, secondary mutations in tumor suppressors, such as STK11 and CDKN2A, contribute to the KRAS independency in lung cancer cell lines." (PMID 34680229, 2021). "Inhibition of FAK can selectively induce KRAS-mutant cell death and lead to KRAS-mutant lung cancer regression." (PMID 34012925, 2021). "Analysis of mRNA levels from the CCLE database showed that the expressions of YAP (YAP1) and TAZ (WWTR1) were upregulated in KRAS-mutant lung cancer cells, compared to KRAS wild-type tumor cells." (PMID 34073318, 2021).
lung cancer (continued). "Over the last few years, breakthroughs have been made in identifying novel strategies to target KRAS and lung cancer has been a primary model of study to determine the effectiveness of these new agents." (PMID 33801965, 2021). "A number of oncogenic driver mutations have been identified in lung cancer with the EGFR and KRAS mutations as the most prevalent and with significant clinical implications." (PMID 33652978, 2021). "The roles of miR-193a-3p in cancer progression have been reported that it inhibits the proliferation and migration of lung cancer and colorectal adenocarcinoma cells by targeting kirsten rat sarcoma viral oncogene (KRAS)." (PMID 33628829, 2021). "Intriguingly, increased Bak expression was observed in tumor tissues from KL mice as compared to adjacent normal lung tissues, thereby providing a strong rationale to employ Bak agonist BKA-073 for the treatment of mutant KRAS-driven lung cancer." (PMID 34373755, 2021). "Mechanistically, SOD1 regulates co-localization of PeBoW with and processing of pre-rRNA, and maturation of cytoplasmic 60S ribosomal subunits in KRAS mutant lung cancer cells." (PMID 33859191, 2021). "Of note, in lung cancer, the mutations in EGFR and KRAS (the two most common ones) are considered mutually exclusive." (PMID 34440587, 2021). "Meanwhile, patients with KRAS G12C lung cancer are likely to find success with covalent inhibitors such as AMG 510 and MRTX849, an anti-endogenous protein degradation molecule." (PMID 35070984, 2021). "For example, dysfunction of NK cells can be caused by induction of the glycolysis-inhibiting enzyme fructose-bisphosphatase 1 (FBP1) which leads to tumor progression in KRAS-driven models of lung cancer." (PMID 33995422, 2021). "In contrast, the roles of LOX- or LOX-derived lipid mediators in lung cancer, especially KRAS-driven lung cancer, remain to be elucidated." (PMID 34635780, 2021). "Mutations of RAS family genes (KRAS, NRAS, and HRAS) are frequently observed in various tumors, including lung cancer, pancreatic cancer, and colon cancer." (PMID 34858498, 2021). "In conclusion, we successfully established nine PDXs of lung cancer patients, of which ADC tumors bearing the KRAS-G12C mutation were the most frequently engrafted." (PMID 34198671, 2021). "Results showed that the mRNA expression of PD-L1 (CD274) was higher in KRAS-mutant lung cancer cells than in KRAS wide-type (WT) cells, and Western blot analysis showed a higher tendency of PD-L1 protein level in KRAS mutant H441 and H460 cells." (PMID 34073318, 2021). "In mutant KRAS‐driven lung cancers, inactivation of PI3Kα yielded only a partial response, MAPK pathway activity being key in this context." (PMID 34033220, 2021). "In this review we aim to give an overview on KRAS role in lung cancer pathogenesis and targeting with a special focus on new potential treatments based on epigenetic modulation." (PMID 35004317, 2021). "With these methods we interrogate the remodelling of the TME induced by a KRAS G12C inhibitor in an immune competent mouse orthotopic lung cancer model, highlighting the infiltration and activation of antigen presenting cells and effector cells." (PMID 34625563, 2021). "This is in line with previous data from both human and murine lung cancer, in which CASC1/Casc1 mutations were shown to often coincide with oncogenic KRAS/Kras." (PMID 33671932, 2021). "Further validation assays using 16 cell lines (8 KRAS-mutant cell lines and 8 WT cell lines) supported the effect of verteporfin as a specific tumor growth inhibitor of KRAS-mutant lung cancer cells." (PMID 33830081, 2021). "The mutually exclusive events, including BRAF and KRAS mutations (two members of MAPK–ERK pathway), are mutual exclusivity and undergo genetic alterations in lung cancer patients." (PMID 34076361, 2021). "Our research found negative correlations between SDPR, PD-L1, and immune cells in KRAS-mutant lung cancers." (PMID 33435990, 2021).
lung cancer (continued). "It is highly expressed in various tumors including breast, colorectal, kidney, prostate, non-small cell lung carcinoma, KRAS-induced lung cancer, and targeting AurB kinases displayed inhibition of cancer progression." (PMID 33540939, 2021). "Together, these observations indicate that PeBoW complex is a key effector for SOD1 to control oncogenic KRAS-driven lung cancer cell proliferation through pre-rRNA processing and 60S ribosome biogenesis." (PMID 33859191, 2021). "Further corroborating the antagonistic role of autophagy, the clinically approved autophagy inhibitor chloroquine potently enhances the cytotoxicity of FGFR1/PLK1 inhibitors in KRAS‐mutant lung cancer cells in vitro and in vivo." (PMID 34369083, 2021). "Together, these data suggest that verteporfin treatment induced ER stress in KRAS-mutant lung cancer cells." (PMID 33830081, 2021). "Our research originally found downregulation of SDPR in lung cancers as well as in KRAS-mutant subgroup, and innovatively explored the immune checkpoint molecules and abundance of immune infiltrations at different SDPR expression and CNVs models." (PMID 33435990, 2021). "These KrasG12D-positive samples showed highly elevated BLT2 expression, in agreement with the contributory role of BLT2 in KRAS-driven human lung cancer." (PMID 34635780, 2021). "They showed that a protein called BLT2 is highly expressed in KRAS-mutant lung cancer cells, and appears to contribute strongly to KRAS-mediated inflammation and tumor growth in mouse models." (PMID 34635780, 2021). "A well-known pair of genes that validates our mutual exclusion data is KRAS with mutated EGFR loci, most commonly seen in lung cancer." (PMID 34204917, 2021). "Exosomes isolated from mutant KRAS lung cancer cells are found to facilitate the switch of naïve CD4+ T cells into Tregs, which is also observed after the transfection of mutant KRAS cDNA." (PMID 34616851, 2021). "FGFR aberrations have also been identified as key compensatory bypass mechanisms of resistance to targeted therapy against mutant epidermal growth factor receptor (EGFR) and mutant Kirsten rat sarcoma 2 viral oncogene homolog (KRAS) in lung cancer." (PMID 34068816, 2021). "Even though MitoQ and MitoTEMPO had no impact on malignant melanoma, they actually tended to increase tumor burden compared with untreated mice with KRAS-induced lung cancer." (PMID 33499262, 2021). "Clinical attempts to target the MAPK pathway have previously focused on MEK, but disappointingly these inhibitors have proven to have limited therapeutic activity in KRAS-mutant lung cancer patients." (PMID 33466360, 2021). "These analyses indicate that two key regulators of the mTOR pathway, STK11 and PTEN, have different functions in lung cancer biology and that KRAS and PTEN are mutually exclusive." (PMID 33652656, 2021). "We next investigated the relative expression levels of the two KRAS splice isoforms in KRAS mutant human lung cancer data sets." (PMID 34257283, 2021). "Specific EMT regulation induced by YAP1 with oncogenic KRAS was shown in a murine lung cancer model." (PMID 33830081, 2021). "Collectively, our results suggest that BLT2 is a potential contributor to KRAS-driven lung cancer and identify an attractive therapeutic target for KRAS-driven lung cancer." (PMID 34635780, 2021). "EGFR-TLI treatment of patients with KRAS mutations lacks efficacy, which indicates the different patterns of EGFR and KRAS gene mutations in lung cancer patients." (PMID 34217313, 2021). "Compared to the TCGA data, the Nanjing Lung Cancer Cohort (NJLCC) and CHOICE cohort of Chinese patients revealed higher rates of EGFR and RB1 mutations, and lower rates of KRAS, BRAF, and STK11 mutations, in adenocarcinoma patients." (PMID 34195081, 2021). "We applied these methods to study the effects of MRTX1257, a mutant-specific inhibitor of the KRAS G12C oncoprotein, on the TME of an immunotherapy refractory KRAS G12C mutant lung cancer." (PMID 34625563, 2021).
lung cancer (continued). "The tumorigenic function of PERK/p-eIF2α arm prompted us to investigate the therapeutic potential of its pharmacological inhibition in the treatment of KRAS-driven lung cancer." (PMID 34330898, 2021). "Due to the limited data dedicated to the evaluation of the RAS genes expression in lung cancer, in current study the assessment of relative KRAS and HRAS gene expression level was performed." (PMID 33549031, 2021). "Screening was done using KRAS-driven pancreatic and lung cancer cell lines treated with MEK1/2 inhibitors (MEKi)." (PMID 34781949, 2021). "Other inhibitors against KRAS have been identified over the last couple of years that show promising results in lung cancer." (PMID 33801965, 2021). "MRTX849 was shown to be an effective monotherapy in lung cancer cells lines and KRAS mutant lines showed to be more sensitive than wild-type cell lines." (PMID 33801965, 2021). "Taken together, our results highlighted the potentially novel mechanism of verteporfin, a critical regulator, in KRAS-mutant lung cancer cells, which involves unresolved ER stress." (PMID 33830081, 2021). "In the present study, we demonstrated that the BLT2 cascade is critical for the progression of KRAS-driven lung cancer." (PMID 34635780, 2021). "First, KRAS-mutant lung cancer cells underwent verteporfin treatment; KRAS-mutant lung cancer cells also underwent siRNA-mediated knockdown of YAP1." (PMID 33830081, 2021). "Next, we used a well-established immunocompetent transgenic mouse model of KRAS mutant lung cancer driven by Adeno-CMV-Cre-mediated induction of KRAS G12D50." (PMID 34853306, 2021). "Our group has recently profiled a large Nova Scotian lung cancer patient cohort for major driver mutations in lung cancer (EGFR, ALK, KRAS, BRAF, and PIK3CA)." (PMID 33956842, 2021). "MET exon 14 is more frequently found in older patients than in patients with EGFR- or KRAS-mutant lung cancer." (PMID 34660325, 2021). "We previously showed that combining the anti-estrogen fulvestrant with the pan-HER inhibitor dacomitinib reduced ER/HER crosstalk and produced synergistic anti-tumor effects in immunocompromised lung cancer models, including KRAS mutant adenocarcinoma." (PMID 35008514, 2021). "The ability of F+D to induce an inflamed TME and upregulate PD-1, both highly predictive factors for sensitivity to anti-PD-1 agents, makes F+D an attractive regimen to administer in KRAS+/ER+ lung cancer prior to an ICB." (PMID 35008514, 2021). "EGFR, KRAS, and PIK3CA gene mutations have a correlation with the clinical characteristics of lung cancer patients, which should be further accepted and improved to enhance the efficacy for personalized cancer treatment." (PMID 34217313, 2021). "Sequential triple therapy has potential for treating lung cancer that shows limited response to current therapies, such as KRAS mutant lung adenocarcinoma." (PMID 35008514, 2021). "Next, we explored functional relationships between LKB1 and ALKBH5 in KRAS mutant lung cancer cells." (PMID 34016959, 2021). "The SHC1, FKBP4, NRAS, and KRAS had higher expressions in lung cancer tissues compared with lung normal tissues in LUAD." (PMID 33936178, 2021).